IGF1 (insulin like growth factor 1)
Diseases named in the same sentence as IGF1 in open-access papers (continued):
Sharing a sentence is not in itself a finding about the gene and the disease.
Obesity (continued). "Indeed, we show that feeding mice a diet supplemented with sodium selenite results in an MR-like phenotype, marked by protection against diet-induced obesity, as well as altered plasma levels of IGF-1, FGF-21, adiponectin, and leptin." (PMID 33783357, 2021). "However, the underlying molecular links among DLK1, IGF1/IGF1R signaling pathway, and miRNA-379/miR-544 cluster in obesity-mediated metabolic dysfunction, like NAFLD, are mostly poorly understood." (PMID 34527673, 2021). "This growth acceleration may be driven by growth factors, such as IGF-1 that is closely related to growth and suspected to be dysregulated in obesity." (PMID 34386750, 2021). "We aimed to compare leptin, ghrelin, adiponectin and insulin-like growth factor-1 (IGF-1) levels of pre-feed and post-feed breast milk in mothers with obesity and normal weight, and tried to determine their effects on infants’ growth over weight for length z-score." (PMID 34348809, 2021). "Our results in patients with CLD are contrary to findings in children with idiopathic, hyperleptinemic obesity who typically have normal or high IGF1 that decreases with weight loss, and suggest that in patients with CLD leptin increases IGF1 levels and promotes linear growth." (PMID 34002033, 2021). "The study does not assess the presence of other associated disorders that may have contributed to the reduction of IGF-1 such as obesity, hepatic and renal dysfunction or acidosis." (PMID 34220703, 2021). "However, further researches are mandatory to convincingly disclose the effects of the insulin/IGF-1 or adiponectin signaling pathways on ISCs response in obesity regarding tumor initiation." (PMID 33827616, 2021). "Importantly, obesity and high levels of insulin and IGF-1, in addition to a diagnosis of diabetes mellitus are associated with worse survival in cancer." (PMID 34684421, 2021). "In addition, the effect of other obesity-related signaling molecules on lung cancer development such as insulin, insulin-like growth factor-1, adiponectin, steroid hormones, and cytokines needs to be elucidated." (PMID 33708630, 2021). "The insulin/IGF-1 signaling pathway may be involved in modulation of intestine epithelium hemostasis following obesity." (PMID 33827616, 2021). "PP in children with an altered body composition may also depend on peripheral mechanisms: IGF-1 activation, adrenal androgen overproduction typical of obesity, and increased conversion of androgens to estrogens due to the aromatic action of adipose tissue." (PMID 34947884, 2021). "The insulin/IGF-1 system is one of the potential “engineers” of many obesity related cancers." (PMID 34208601, 2021). "Impaired DNMT1-dependend promoter methylation increases the expression of various developmental genes including insulin (INS), IGF-1 (IGF1) and fat mass- and obesity-associated gene (FTO), which all promote insulin/IGF-1-PI3K-AKT- and FTO/amino acid-mediated activation of mTORC1." (PMID 33803410, 2021). "The obesity-related changes include a chronic state of low-grade inflammation, adipokine imbalances, elevated levels of growth factors, and hormones, such as insulin, insulin-like growth factor (IGF)-1, and estrogens." (PMID 34631264, 2021). "Thus, this study aims to compare leptin, ghrelin, adiponectin and IGF-1 levels of pre-feed and post-feed breast milk in mothers with obesity and normal weight." (PMID 34348809, 2021). "The same group suggested that the consumption of a high-protein breakfast could prevent obesity through the up-regulation of IGF-1, particularly in T2DM." (PMID 34684432, 2021). "Several shared molecular, genetic and environmental risk factors are known in the pathomechanism of T2DM and CRC, for example obesity, decreased vitamin D- and increased insulin like growth factor 1 serum concentration, older age, increase of inflammatory pathways, epigenetic changes, etc.." (PMID 32121060, 2020).
Obesity (continued). "Evidence suggests that obesity promotes CRC by activating the insulin/IGF-1 signaling pathway." (PMID 33346251, 2020). "As IGF1 exerts neuroprotective and anti-inflammatory effects, obesity or nutrition-induced modifications in this system could be involved in hypothalamic inflammation and central metabolic control." (PMID 32849298, 2020). "Some direct and indirect mechanisms by which exercise affects cancer are further discussed by Thomas, however we would like to explore those somehow connected to obesity such as energy metabolism and insulin resistance, leptin, IGF-1, chronic inflammation and obesity-related hormones and cytokines." (PMID 33371214, 2020). "Partly, these results may be attributed to the increased production of estrogen secondary to the aromatase activity in breast adipose tissue; additionally, obesity increases inflammatory cytokines, circulating insulin, and IGF-1 levels." (PMID 33180852, 2020). "The adipose tissue of children with overweight/obesity might lead to an increase in growth hormone and IGF-1, thereby affecting skeletal maturation." (PMID 32988365, 2020). "An association between OSA and lower GH and IGF-1 levels has been previously reported, independent of obesity." (PMID 32655494, 2020). "Researchers have found that obesity promotes the expression of insulin and insulin-like growth factor-1 (IGF-1), causing the transformation of non-advanced colorectal polyps to advanced polyps and triggering recurrence." (PMID 32967679, 2020). "Obesity-related hyperinsulinaemia increases IGF-1 and inhibits IGFBP-2 secretion." (PMID 32586279, 2020). "Insulin and insulin-like growth factor-1 stimulate specific responses in arteries, which may be disrupted by diet-induced obesity." (PMID 30295509, 2019). "In addition to the significant differences observed in serum adipokines, fasting glucose levels, insulin levels, and glucose tolerance, obesity was also associated with elevated serum levels of IGF-1, IGF-1/IGFBP2, and IGF-1/IGFBP3 in HFD-Obese mice." (PMID 30867005, 2019). "Thus, the strong point of our study is that we highlighted the therapeutic role of nutrition on the obesity-related GH/IGF-1 axis derangements." (PMID 31527400, 2019). "The current findings are comparable with the results from a previous study which reported that OA activates insulin receptor-1 (IR-1) which lowers circulating insulin and IGF-1 levels and subsequently reduces cardiac hypertrophy in animal models of obesity and metabolic syndrome." (PMID 30669379, 2019). "Obesity starts in utero and continues even during long-term IGF1 treatment." (PMID 31208077, 2019). "A balanced and healthy diet may control all the factors that have been described to sustain obesity-related disease (i.e., IGF-1, insulin, leptin)." (PMID 31052147, 2019). "This can be explained by the higher levels of IGF-1 in obesity, which is the real hormone responsible for growth, just as early puberty in these cases can be explained by the increase in IGF-1 itself and the high levels of leptin produced by the excessive fat tissue." (PMID 31379735, 2019). "Recent studies have suggested that inflammatory mediators could play a relevant role in the decrease in IGF-1 bioactivity, which could be related to obesity which is characterized by a chronic low-grade inflammation." (PMID 31608009, 2019). "For example, obesity-induced hyperleptinemia and increases in insulin/IGF-1 levels, as observed in the present study and in other models, can lead to activation of phosphoinositide 3-kinase and mammalian target of rapamycin (mTOR) signaling and promote primary tumor growth." (PMID 30867005, 2019). "The effects of obesity on IGF-1 levels are more controversial." (PMID 31130916, 2019). "Fourth, additional hormonal assessment including sex steroids, IGF-1 and hormones modulating satiety such as leptin and ghrelin, may further explain the differences in obesity rates with abnormal sleep habits." (PMID 30971731, 2019).
Obesity (continued). "In fact, low levels of IGF-1 are related with obesity and impaired glucose tolerance." (PMID 29495516, 2018). "Despite experimental and observational evidence supporting a role for IGF‐1 signaling in CRC development 13, 14, 15, our study did not provide evidence that weight loss in individuals with obesity reduces circulating concentrations of IGF‐1." (PMID 29086510, 2017). "Regarding other growth factors related to both obesity and cachexia, our group showed that serum IGF-1 concentration increases in trend after surgery and is associated with a risk for developing post-load hypoglycemia 2 h after a standardized glucose challenge." (PMID 27900559, 2017). "Interestingly, obesity courses with the dysfunction of key regulatory systems, including GH, insulin and IGF1 axes, which are crucial for the correct development and maintenance of several organs 29, including the PG." (PMID 28244645, 2017). "Our findings suggest that in obesity, insulin and IGF1 signaling pathway cross-talks with IL-17 signaling pathway through suppressing GSK3 activities, thus enhancing IL-17-mediated inflammation and contributing to the chronic inflammatory status commonly seen in obesity." (PMID 26871944, 2016). "Such improvement promotes lipogenesis in fat (recall that IGF-1 could maintain cytokine homeostasis—anti-inflammatory effects-, and thus protection from mild inflammation as a consequence of obesity)." (PMID 26733412, 2016). "Abnormal IGF-1 and GH levels have been proposed to play a key role in obesity." (PMID 26733412, 2016). "Likewise, anti-inflammatory actions of IGF-1 can be regarded as a crucial factor protecting tissues from the deleterious effects of pro-inflammatory mediators in chronic disorders such as obesity." (PMID 26733412, 2016). "Obesity could potentially alter the levels of multiple hormones and growth factors (e.g., testosterone, estrogen, leptin, insulin, and IGF-1) with competing effects on prostate growth and size." (PMID 27409334, 2016). "Therefore, obesity performs a complex biological activity regulation like cytokines production leading insulin resistance or deregulation of IGF1 and immune system among others." (PMID 26801617, 2016). "Interestingly, α-NF, at concentrations greater than 2.5 μM, nearly completely inhibited IGF-1 secretion, although IGF-1 was indicated to be positively associated with cancers and obesity." (PMID 25942489, 2015). "IGF-1 has long been regarded as one of the adipocyte differentiation stimulators, and extensive studies have been conducted to study its exact roles on growth, obesity and disease development." (PMID 25675096, 2015). "Subject to a minimum threshold of four rGSSs, genes present in at least one of the obesity or IGF1 tGSSs could be considered as SC gIDs." (PMID 26100469, 2015). "Next, we studied both the obesity and IGF1 tGSSs of BC with respect to the MAPK signalling pathway." (PMID 26100469, 2015). "We further established that these diets altered several biological pathways previously hypothesized to be involved in obesity and cancer, including inflammation, IGF-1, adipokines, and microRNAs." (PMID 24732966, 2014). "Thus, our in vitro results further point out for a central role of IGF-1 and osteoblasts disruption in the mechanisms linking obesity to decreased bone quality." (PMID 24963291, 2014). "In human, obesity can lead to marked changes in the growth hormone (GH)—IGF-1 axis." (PMID 27433503, 2014). "Other contributors to obesity-related cancer progression are insulin/IGF-1 pathways and hormones." (PMID 25505738, 2014).
Obesity (continued). "We conclude that components of the IGF-1 signaling and inflammatory cytokine pathways (and potentially the cross-talk between these pathways) should be considered in future studies of targets and strategies for preventing obesity-related colon cancer." (PMID 24732966, 2014). "Administering rhGH in small doses is able to stabilize IGF-1 levels in obesity." (PMID 25435886, 2014). "The present study demonstrated that the obesity-related conditions of elevated glucose, insulin and IGF-1 levels may increase cell viability and in selected cases, resistance to chemotherapy and accumulation of the global transcription factor, HIF-1." (PMID 24396438, 2014). "Several other growth factors and cytokines upregulated in obesity, such as IL-6, IL-8, IGF-1, and TGFβ, may also influence prostate cancer cell proliferation." (PMID 23573093, 2013). "Furthermore, we examined pharmacokinetics and pharmacodynamics and monitored growth of MC38 cell allografts in mice with diet-induced obesity treated with human insulin, X10 and IGF-1." (PMID 24260289, 2013). "Human observational studies have reported increased cancer mortality in those with obesity and type 2 diabetes, which may be attributable to hyperinsulinemia, elevated IGF-1, or potentially both factors." (PMID 23050962, 2012). "Surprisingly, the finding that the administration of exogenous leptin elevates IGF-1 and TGFβ secretion by rat knee joint cartilage may suggest that increased plasma leptin levels in obesity protect cartilage against degeneration." (PMID 22584415, 2012). "The IGF-1 is involved in androgen-independent progression of prostate cancer and leptin induces migration in prostate cancer cells, thus obesity-induced hormonal changes may promote tumour progression." (PMID 21266978, 2011). "Despite these limitations, our study demonstrated a consistent and significant relationship among the serum markers of obesity measured (insulin, C-peptide, IGF-1, adiponectin, BMI), supporting the conclusion of a limited relationship between obesity and colorectal cancer survival." (PMID 21081932, 2011). "We have shown an association between obesity, inflammation, angiogenesis and outcome, but not demonstrated a role of the insulin-IGF-1 axis." (PMID 21081932, 2011). "However, the possible effects of obesity and insulin-IGF-1 on response to chemotherapy treatment warrant further study." (PMID 21081932, 2011). "Hence it is possible that in obesity IGF-1 can affect tumor development both directly, by stimulating tumor growth and indirectly, by creating a microenvironment that is permissive for tumor growth." (PMID 21696633, 2011). "Our finding of an association between BMI and both colon and rectum cancers in men supports earlier observations and may be due to the growth-promoting effects of insulin and insulin-like growth factor (IGF-1), both increased in obesity." (PMID 16234822, 2005). "Additionally, obesity, socioeconomic deprivation, elevated C-reactive protein, triglyceride, vitamin D, HbA1c, cystatin C, urate, and alanine aminotransferase, and decreased HDL cholesterol and IGF-1, as well as CKD and COPD, were associated with LC." (PMID 40738888, 2025). "Moreover, hyperinsulinemia may foster mitogenic MAP kinase-related signaling, which can also occur via IGF1 receptors due to increased free IGF1 levels in obesity." (PMID 40277890, 2025). "In a recent study of Norwegian children and adolescents, blood concentrations of leptin, IGF-1 and triglycerides were also positively associated with each-other and negatively associated with HDL-cholesterol concentrations, and were particularly elevated in children with overweight/obesity." (PMID 39899498, 2025). "Third, our study focused on the effects of exercise on C-peptide and IGF-1 levels as mediators of the observed outcomes; however, other factors and mechanisms may contribute to the regulation of body composition and physical fitness in children with obesity." (PMID 39822775, 2024).
Obesity (continued). "In addition, a number of other risk factors are shared in the development of OA and bladder cancer, such as obesity and metabolic syndrome, coffee consumption, higher serum IGF‐1 concentration, Brazilin, Chondromodulin‐1,59 vitamin K‐dependent protein, and GRP/Ucma." (PMID 38100139, 2023). "No clear relationship between the levels of IGF-1 or GH and tumor development could be demonstrated, but certain risk factors, such as diabetes mellitus (DM) and obesity, were more frequent in patients with tumors." (PMID 37374352, 2023). "Given that IGFBP3 as the inhibitor of IGF1 bioavailability and activity has a vast array of biological functions and is involved in IR, obesity, inflammation, and oxidative stress, it seems reasonable to assume that its gene (IGFBP3) may contribute to the development and progression of NAFLD." (PMID 37948568, 2023). "Finally, we address the challenges and limitations of targeting GH and IGF-1 in obesity management." (PMID 37298507, 2023). "Thus, potential mechanisms underlying the association of obesity with CRC pathogenesis include adipocytokine imbalance, insulin resistance, changes in the insulin-like growth factor (IGF)-1/IGF-1 receptor (IGF-1R) axis, and chronic inflammation and oxidative stress." (PMID 37048534, 2023). "Moreover, it is important to note that animal models may not necessarily be directly applicable to humans, and more clinical trials are needed to fully evaluate the potential benefits and risks of GH and IGF-1 therapy in managing obesity." (PMID 37298507, 2023). "In conclusion, GH and IGF-1 may offer a promising avenue for the management of obesity, but caution should be exercised, and more research is needed to fully understand their effects, develop safe and effective treatment strategies, and validate their findings in human populations." (PMID 37298507, 2023). "There is critical need for more studies describing intracellular signaling, transcription/translation, insulin/IGF-1 signaling, as well as the roles of plasma and muscle lipids, and amino acid delivery/blood flow in regulating protein synthesis and breakdown in muscle of humans with obesity." (PMID 35350688, 2022). "It is important to mention that based on our analyses we cannot entirely exclude that GHBP and IGF-1 released from AT might contribute to obesity-related elevations in the serum levels, as the amount of protein released from cells is not necessarily reflected by its gene expression." (PMID 36384443, 2022). "However, while it has been shown that certain proinflammatory cytokines such as TNFα and IL-1β induce hepatic IGF-1 resistance, the contribution of IL-6 signaling in obesity-induced inflammation to hepatic insulin and IGF-1 downstream signaling remains controversial." (PMID 35628414, 2022). "Also, lower response of muscle IGF-1 expression to resistance exercise in humans with obesity may explain blunted response of muscle protein synthesis observed in humans with obesity after resistance exercise." (PMID 35350688, 2022). "Therefore, decreased expression of IGF-1 may not only contribute to obesity, but also have an important impact on ARHL by affecting mitochondrial function." (PMID 35966796, 2022). "Besides OSA, there were several factors that may affect GH/IGF-1 levels, such as age, genetics, psychological factors, exercise, obesity, nutritional intake, smoking and alcohol status, and even sleep duration." (PMID 36699292, 2022). "However, this seems unlikely to explain our findings on changes in obesity in men because reduction in visceral obesity has been found to be associated with increased IGF‐1 levels in men." (PMID 35049043, 2022). "In addition, how obesity affects hearing may also be related to insulin-like growth factor 1 (IGF-1)." (PMID 35966796, 2022).